MIF (macrophage migration inhibitory factor)
Diseases named in the same sentence as MIF in open-access papers (continued):
Sharing a sentence is not in itself a finding about the gene and the disease.
leptospirosis (continued). "In this study, our observations clearly stated that MIF ELISA has high sensitivity (100%) and specificity (>90%) for the diagnosis and distinction of leptospirosis cases from other febrile cases." (PMID 35237527, 2021). "Thus, the present findings provide the framework for further studies for understanding the role of MIF in leptospirosis." (PMID 35237527, 2021). "To identify whether MIF protein was differentially expressed between leptospirosis patients and healthy control subjects, we used the sera of the study subjects to assess circulating MIF concentrations with MIF ELISA." (PMID 35237527, 2021). "As there is still no remarkable severity predictor for leptospirosis, it is assumed that our significant range of elevated serum MIF may serve as a potential predictor of severe leptospirosis." (PMID 35237527, 2021). "Pearson’s correlation test demonstrated that the serum MIF levels were strongly correlated (r = 0.75) with disease duration, directly indicating that MIF might be deeply involved in the pathology of leptospirosis." (PMID 35237527, 2021). "MIF had an AUC value of >0.9 for the different outcomes of leptospirosis." (PMID 35237527, 2021). "The analysis suggested that serum MIF may serve as a severity predictor of human leptospirosis." (PMID 35237527, 2021). "The difference in the serum MIF levels between leptospirosis cases with febrile illness (mild, non-hospitalized) and those with organ dysfunction (severe, hospitalized) was significantly high (2.5, p < 0.001)." (PMID 35237527, 2021).
Lipedema (2 papers, 2023 to 2025). Disorder of adipose tissue characterized by symmetric and bilateral enlargement of the lower extremities due to abnormal deposition of subcutaneous fat often in obese women. "Given the predominant presence of macrophages in lipedema, an involvement of the MIF axis regarding the pathophysiology of lipedema seems logical." (PMID 37887430, 2023). "Consistent with our findings, lipedema has been characterized by an increased population of M2‐polarized macrophages (referred to as “alternatively activated”) and a state of low‐grade inflammation, along with elevated levels of macrophage migration inhibitory factor." (PMID 40077894, 2025).
memory impairment (2 papers, 2019 to 2023). "MIF deficiency resulted in memory impairment on the Morris water maze whereas overexpression of MIF preserved neural cells from Aβ toxicity." (PMID 38073631, 2023). "In the hidden platform test, APP23/MIF+/− mice showed significant memory impairment on the fifth day of the test." (PMID 31174614, 2019).
mesothelioma (2 papers, 2016). A usually malignant and aggressive neoplasm of the mesothelium which is often associated with exposure to asbestos. "In mesothelioma cells, high MIF levels were associated with a high multiplication rate of cells." (PMID 26883190, 2016). "All these data highlight the complexity of the MIF/CD74 signaling pathway in the development of mesothelioma." (PMID 26883190, 2016). "In vitro, reduction of MIF or CD74 levels in both mesothelioma cell lines showed that the MIF/CD74 signaling pathway promoted tumor cell proliferation and protected MPM cells from apoptosis." (PMID 26883190, 2016). "syngeneic implantations of murine mesothelioma cells deleted or not in MIF or CD74 expression into wild-type or MIF-deficient or CD74-deficient mice and study tumor development, tumor angiogenesis and identify the inflammatory cells recruited by the host." (PMID 26883190, 2016). "In the present study, we compared the levels of expression of MIF and CD74 in different human mesothelioma cell lines and investigated their physiopathological functions in vitro and in vivo." (PMID 26883190, 2016). "Human mesothelioma cells expressed more CD74 and secreted less MIF than non tumoral MeT5A cells, suggesting a higher sensitivity to MIF." (PMID 26883190, 2016).
metastatic cancer (2 papers, 2021 to 2024). A carcinoma which has spread from the original site of growth to another anatomic site. "The VCAM pathway, GDF pathway, MIF pathway, TNF pathway, CD137 pathway and ITGB2 pathway specifically appeared in metastatic cancer." (PMID 38365757, 2024).
metastatic colorectal cancer (2 papers, 2017 to 2020). "In a clinical trial for metastatic colorectal cancer, imalumab (BAX69), a mAb that identifies MIF is used in combination with panitumumab (NCT02448810)." (PMID 29312320, 2017).
mood disorder (2 papers, 2014 to 2021). A cognitive disorder a disturbance in which the person's mood is hypothesized to be the main underlying feature. "According to the neurodevelopmental and neuroimmunological hypotheses of mood disorders, we analyzed serum levels of brain-derived neurotrophic factor (BDNF), proBDNF, epidermal growth factor (EGF), migration inhibitory factor (MIF), stem cell factor (SCF), and correlations with clinical factors." (PMID 34575175, 2021). "Our results did not support the role of MIF in adolescent mood disorders." (PMID 34575175, 2021).
Multiple Organ Failure (2 papers, 2021). A progressive condition usually characterized by combined failure of several organs such as the lungs, liver, kidney, along with some clotting mechanisms, usually postinjury or postoperative. "In rodent models, infusion of MIF could lead to multiple organ failure and even death, which could be reversed by anti-MIF antibodies." (PMID 33482739, 2021). "In addition, serum MIF levels were significantly raised in patients who developed pancreatic necrosis or multiple organ failure, indicating MIF could act as a sensitive biomarker to predict local and systemic complications for AP." (PMID 33776775, 2021).
Myocardial fibrosis (2 papers, 2019 to 2025). "Additionally, MIF appears to exert a certain improvement effect in myocardial fibrosis." (PMID 41357167, 2025).
myocarditis (2 papers, 2013 to 2024). Myocarditis is a condition that is characterized by inflammation of the heart muscle (myocardium). "The macrophage migration inhibitory factor (MIF), an essential proinflammatory cytokine, is recognized to be involved in inflammatory CV diseases, such as myocarditis and septic cardiomyopathy." (PMID 39144689, 2024).
nasal polyps (2 papers, 2015 to 2021). "Other researchers have also found that the use of an MIF inhibitor decreased IL-6-mediated inflammation in nasal polyps." (PMID 25705692, 2015).
Neonatal sepsis (2 papers, 2017 to 2022). Systemic inflammatory response to infection in newborn babies. "However, the role of MIF in neonatal sepsis remains unclear." (PMID 36042599, 2022).
neurosyphilis (2 papers, 2022 to 2023). Infection of the brain or spinal cord by Treponema pallidum. "Meanwhile, the increased levels of CXCL9, CXCL7, CCL24, IL-17, IL-26, and migration inhibitory factor (MIF) of macrophages in the CSF of neurosyphilis patients suggested their role as promising differential diagnostic tools for neurosyphilis." (PMID 38105236, 2023). "MIF concentration can be considered as a new potential CSF indicator to establish or exclude the diagnosis of neurosyphilis, but further studies are needed." (PMID 36452956, 2022). "Studies have shown that the sensitivity of CSF MIF concentration for neurosyphilis diagnosis was 74.42%, and the specificity was 67.74%." (PMID 36452956, 2022). "MIF has been considered a new potential CSF indicator to establish or exclude the diagnosis of neurosyphilis, but further study is needed." (PMID 36452956, 2022). "The MIF level was higher in the CSF of neurosyphilis patients than in syphilis/non-neurosyphilis patients." (PMID 36452956, 2022). "Interleukin, MIF, Tau protein, BACE1, sTREM2, and β2-microglobulin and metagenomic and metabolomic factors are considered to be potential markers in the CSF detection of neurosyphilis." (PMID 36452956, 2022).
plaque psoriasis (2 papers, 2018 to 2021). "This study aimed to determine the association between the SNP ‐173 G>C and STR ‐794 CATT5‐8 polymorphisms of the MIF gene with MIF serum levels and the risk of presenting plaque psoriasis in a Mexican mestizo population." (PMID 34533238, 2021). "Our objective was to investigate the MIF polymorphisms as a risk factor for plaque psoriasis (PP) in the Mexican population." (PMID 34533238, 2021). "Furthermore, with MIF implicated in atherogenesis, which is purportedly aggravated by plaque psoriasis, MIF may be a common pathogenic pathway of both diseases." (PMID 30333830, 2018). "The high expression of MIF and its cellular pattern in lesional skin, found here, are additional features these models have in common with human plaque psoriasis." (PMID 30333830, 2018). "Daily treatment with AldaraTM cream, containing imiquimod, markedly increased the abundance of MIF in the skin and generated a cellular skin expression pattern of MIF closely resembling that in human plaque psoriasis." (PMID 30333830, 2018). "Hence, MIF inhibitors may synergize with topical glucocorticoids, which are still the mainstay in the treatment of acute flares of plaque psoriasis, thus, sparing glucocorticoid toxicity." (PMID 30333830, 2018).
pneumococcal infection (2 papers, 2022 to 2023). Infections with bacteria of the species streptococcus pneumoniae. "The deficiency of MIF was associated with reduced numbers of macrophages, as well as an impaired upregulation of CCL2 in the respiratory tract, highlighting the role of this immune mechanism in the protection against pneumococcal infection." (PMID 37958756, 2023). "Also, the Gram-positive bacteria streptococcus pneumoniae infection strongly up-regulated MIF production and treatment with the anti-MIF antibodies significantly reduced bacterial loads and improved overall survival." (PMID 35464430, 2022).
polymyositis (2 papers, 2018 to 2019). A rare idiopathic inflammatory myopathy characterized by symmetric proximal muscle weakness and elevated muscle enzymes. "MIF, a pro-inflammatory cytokine, has been implicated in muscle damage, in view of its increased levels in muscle of polymyositis patients." (PMID 29872072, 2018).
proliferative vitreoretinopathy (2 papers, 2022 to 2026). Vitreoretinal membrane shrinkage or contraction secondary to the proliferation of primarily retinal pigment epithelial cells and glial cells, particularly fibrous astrocytes, followed by membrane formation. "Secretion of MIF has been connected to proliferative vitreoretinopathy and it has been shown to enhance migration and proliferation of RPE cells." (PMID 35073969, 2022).
prostate adenocarcinoma (2 papers, 2005 to 2021). "Nevertheless MIF has been found as a cytokine, strongly corresponded with prostate adenocarcinoma and disease progression." (PMID 34157052, 2021). "Additional aims were to examine MIF expression, as well as the location of MIF's receptor, CD74, in human prostatic adenocarcinoma compared to matched benign prostate." (PMID 16000172, 2005).
pyometra (2 papers, 2023 to 2024). "Interestingly, a reduction in interleukin 6 (IL-6) gene expression and macrophage migration inhibitory factor (MIF) in the uterus of cats with pyometra, as well as an increase in the endometrial immunolabeling of IL-10, was observed, suggesting the activation of anti-inflammatory defenses." (PMID 37835759, 2023).
renal carcinoma (2 papers, 2016 to 2025). A carcinoma arising from the epithelium of the renal parenchyma or the renal pelvis. "For instance, a novel class of covalent isothiocyanate-based MIF inhibitors demonstrated strong growth-inhibitory effects in colorectal and renal cancer cell lines." (PMID 40835826, 2025). "In order to determine the effect of radiation on MIF expression in renal cancer cells, western blot analyses of ccRCC cell lines RCC4 and 786-O were performed." (PMID 26741693, 2016). "Our studies have identified a critical role for MIF in renal cancer." (PMID 26741693, 2016). "Like both the renal cancer lines and the MCF7 line, MIF secretion was efficiently induced." (PMID 26741693, 2016).
Renal cyst (2 papers, 2020 to 2024). A fluid filled sac in the kidney. "We tested renal cysts within kidney tissue obtained from the named mouse model for ICA- and HIF-1α-dependent effects on MIF as well as ABCA1 expression by immunohistochemistry." (PMID 32885302, 2020).
rheumatic heart disease (2 papers, 2016 to 2025). An autoinflammatory condition following an infection with Group A Beta Hemolytic Streptococcus (GABHS), in which the heart is attacked by antibodies formed in reaction to a recent GABHS infection. "Although macrophage migration inhibitory factor (MIF) has consistently been shown to be an important immune modulator, data on the association between MIF promoter variations and the risk of developing rheumatic heart disease (RHD) remain inconclusive." (PMID 27014277, 2016).
scrub typhus (2 papers, 2021 to 2024). Scrub typhus is a rare dust mite-borne infectious disease caused by the Orientia tsutsugamushi bacterium and characterized clinically by an eruptive fever which is potentially serious. "We have previously reported that YKL-40 and MIF may contribute to severity and clinical outcome in scrub typhus, possibly related to involvement in endothelial cell activation and adhesion and migration of vascular cells." (PMID 33914733, 2021).
soft tissue sarcoma (2 papers, 2025). A malignant neoplasm arising from muscle tissue, adipose tissue, blood vessels, fibrous tissue, or other supportive tissues excluding the bones. "It has found that tumor cells reshape the heterogeneity of macrophages in the TME by secreting MIF in a soft tissue sarcoma mouse model." (PMID 39891284, 2025).
spinal cord contusion (2 papers, 2021 to 2023). "The levels of cytokines CXCL5, CCL11, CXCL11, IL10, TNFα, and MIF were different between patients with baseline American Spinal Injury Association Impairment Scale (AIS) grades of A or B, whilst IL2 (>2 fold) and MIP-3a (>6 fold) were significantly expressed in the cervical and thoracic regions." (PMID 33806460, 2021). "It is postulated that HIF‐1α is involved in the regulation of MIF following spinal cord injury (SCI)." (PMID 37334735, 2023).
Thrombocytopenia (2 papers, 2006 to 2020). A reduction in the number of circulating thrombocytes. "Platelet-derived MIF may be involved in DENV NS1-induced thrombocytopenia and hemorrhage." (PMID 32545679, 2020).
undifferentiated pleomorphic sarcoma (2 papers, 2025). An undifferentiated soft tissue sarcoma characterized by the presence of a pleomorphic malignant cellular infiltrate. "Experimental data on anti-MIF and anti-APP oncotherapy already exists, with vaccination targeting of APP being discussed as a therapy for several cancers and anti-MIF treatment having potential for treatment of undifferentiated pleomorphic sarcoma." (PMID 41373578, 2025).
acral melanoma (1 paper, 2024). "While little research has described the role of MIF in acral melanoma, it has similarly been hypothesized to drive pathogenesis via the presence of M2-type macrophages in the TME." (PMID 39028303, 2024).
Acute encephalopathy (1 paper, 2021). "A further recent study potentially relevant to NS revealed that CSF levels of MIF are significantly higher in children suffering from acute encephalopathy and having poor-prognosis, than in good-prognosis patients, and suggest that MIF may be markers of poor prognosis." (PMID 34662363, 2021).
acute liver failure (1 paper, 2019). Rapid deterioration of liver function causing encephalopathy and coagulopathy. "CCL11 (Eotaxin) was selectively increased in biliary atresia patients, while IL-3, IL-6, CXCL8 (IL-8), IL-9, IL-16, MIF, CCL4 (MIP-1 β), and CXCL1 (GRO-α), were increased in both biliary atresia and acute liver failure." (PMID 30740106, 2019).
acute lymphoblastic leukemia (1 paper, 2024). Leukemia with an acute onset, characterized by the presence of lymphoblasts in the bone marrow and the peripheral blood. "In vitro and in vivo Acute Lymphoblastic Leukemia (ALL) models reveal that MIF is positively regulated by UHRF1 (ICBP90) and negatively regulated by HBP1, both of which drive MIF overexpression in disease progression by binding to the promotor region." (PMID 38732068, 2024).
Acute otitis media (1 paper, 2020). Acute otitis media is a short and generally painful infection of the middle ear. "It has been found that blocking the activity of MIF by ISO-1 could reduce the inflammation in acute otitis media mice in which process TLR-4 and NF-κB were involved." (PMID 32964038, 2020). "Blocking the activity of MIF by its antagonist 3-(4-hydroxyphenyl)-4,5-dihydro-5-isoxazole acetic acid methyl ester (ISO-1) could reduce the inflammation in acute otitis media mice in which process TLR-4 and NF-κB were involved." (PMID 32964038, 2020).
AIDS (1 paper, 2008). A syndrome resulting from the acquired deficiency of cellular immunity caused by the human immunodeficiency virus (HIV). "MIF concentration was elevated in patients with AIDS related diarrhoea, but was not independently related to mortality." (PMID 19014537, 2008). "Of the five cytokines we studied, only IL-12 appeared not to be elevated in patients with AIDS related diarrhoea, but IL-6 and MIF were not directly related to mortality." (PMID 19014537, 2008).
alcohol (1 paper, 2024). "During alcohol intoxication, damaged hepatocytes also enhance liver inflammation by releasing macrophage migration inhibitory factor (MIF), a multifunctional chemokine promoting the progression of ALD." (PMID 39590862, 2024).
alcoholic liver diseases (1 paper, 2020). A disorder caused by damage to the liver parenchyma due to alcohol consumption. "Notably, hepatocyte-derived MIF was also shown in another model (i. e. alcoholic liver disease) to be a driving force for liver injury." (PMID 32012211, 2020).
allergic contact dermatitis (1 paper, 2022). An inflammatory skin condition caused by an immune response to direct contact between the skin and an allergen. "Further investigation of MIF as a target protein can be a next step to determine if MIF is a biomarker that can be used to develop better diagnostic tools and targeted therapeutics for individuals with allergic contact dermatitis." (PMID 35465102, 2022).
amebiasis (1 paper, 2014). A parasitic infectious disorder caused by amoebas. "Most recently, it was shown that E. histolytica possesses a human-like macrophage migration inhibitory factor (EhMIF) that induces the production of IL-6 that might further contribute to IL-6 production during invasive amebiasis." (PMID 25420932, 2014).
anaplastic thyroids carcinoma (1 paper, 2017). "We have recently observed an extensive alteration of some crucial oncogenic signals and a decrease in Krebs cycle activity through the specific inhibition of MIF activity using 4-IPP in papillary and anaplastic thyroids carcinoma models." (PMID 28114961, 2017).
anxiety depression (1 paper, 2021). "In addition, MIF deficient mice demonstrated behavioral changes compared to normal wild type (WT) mice that resulted in anxiety depression and memory loss." (PMID 34662363, 2021).
Atherosclerotic lesion (1 paper, 2020). A lesion associated with atherosclerosis, a multifactorial and multipart progressive disease manifested by the focal development within the arterial wall of lesions, that ranges from the development of a fatty streak, plaque progression, and plaque disruption. "Alternatively, rs755622 may be mainly related to localized MIF expression, that is, MIF expression can be increased in certain cell types or tissues, such as atherosclerotic lesions." (PMID 32560699, 2020).
Azoospermia (1 paper, 2015). Absence of any measurable level of sperm,whereby spermatozoa cannot be observed even after centrifugation of the semen pellet. "Previous studies on azoospermia or oligozoospermia induced by SHS mainly focused on germ cell apoptosis; no data regarding their possible effect on nitric oxide (NO), nitric oxide synthase (NOS) and macrophage migration inhibitory factor (MIF) in semen are available." (PMID 26512992, 2015).